ECSCR (endothelial cell surface expressed chemotaxis and apoptosis regulator)
Description:
Regulates endothelial chemotaxis and tube formation. Has a role in angiogenesis and apoptosis via modulation of the actin cytoskeleton and facilitation of proteasomal degradation of the apoptosis inhibitors BIRC3/IAP1 and BIRC2/IAP2.
Synonyms: ARIA; ECSM2
Tractability: Antibody: its Gene Ontology location is reachable by antibodies, with high confidence; UniProt places it where antibodies can reach, with medium confidence; UniProt predicts a signal peptide or a membrane-spanning region; the Human Protein Atlas places it where antibodies can reach.
Gene: Protein-coding gene on chromosome 5 (139,446,541 to 139,462,745, reverse strand). Ensembl gene ENSG00000249751.
Subcellular location: Cell membrane; Cytoplasm
Subcellular location (Human Protein Atlas): Plasma membrane; Vesicles; Nucleoplasm
Gene Ontology:
Molecular function: protein binding
Biological process: negative regulation of angiogenesis; positive regulation of endothelial cell apoptotic process; positive regulation of proteasomal protein catabolic process
Cellular component: cytosol; plasma membrane; cytoplasm
Genetic constraint (gnomAD): Loss-of-function variants: 9 observed, 12.36 expected, observed/expected ratio (o/e) 0.73, 90% interval 0.44 to 1.27. The upper end of that interval is the gene's LOEUF score, 1.27, which puts it in group 5 of 6, group 1 being the genes least tolerant of losing a copy. Missense variants: 105 observed, 97.21 expected, observed/expected ratio (o/e) 1.08, 90% interval 0.92 to 1.27. Synonymous variants: 37 observed, 35.04 expected, observed/expected ratio (o/e) 1.06, 90% interval 0.81 to 1.39.
Homologues: Orthologues: chimpanzee ECSCR (88% identical), pig ECSCR (69% identical), rabbit ECSCR (69% identical), rat Ecscr (59% identical), mouse Ecscr (57% identical), guinea pig ECSCR (56% identical).
Diseases named in the same sentence as ECSCR in open-access papers:
ECSCR is named in the same sentence as 6 diseases in open-access papers, as found by Europe PMC text mining. Sharing a sentence is not in itself a finding about the gene and the disease. The quoted sentences say what the papers report.
lung carcinoma (1 paper, 2016). "However, our group has previously found that higher TEM expression levels (Robo4, ECSCR, Clec14) correlated with a prolonged overall survival in primary lung cancer tumor samples." (PMID 26956051, 2016).
metabolic syndrome (1 paper, 2015). A cluster of metabolic risk factors for CARDIOVASCULAR DISEASES and TYPE 2 DIABETES MELLITUS. "ECSCR function seems to describe a control point for fat storage, and thus ECSCR could become a drug target for metabolic syndrome." (PMID 26692198, 2015).
non-small cell lung carcinoma (1 paper, 2016). A group of at least three distinct histological types of lung cancer, including non-small cell squamous cell carcinoma, adenocarcinoma, and large cell carcinoma. "Increased expression of ROBO4, CLEC14A and ECSCR have also been associated with improvements in survival in non-small cell lung cancer." (PMID 26943033, 2016).
Obesity (1 paper, 2025). Accumulation of substantial excess body fat. "The ECSCR gene plays a role in the regulation of insulin sensitivity and susceptibility to obesity." (PMID 40362161, 2025).
tumor (4 papers, 2010 to 2025). "This implies that macrophages play a pro-tumour role by upregulating endothelial genes, which were later identified as ECSCR, ANGPTL4 and ITGB447." (PMID 34732817, 2021). "Importantly, at disease progression, we observed an increase of proangiogenic factors, upregulation of CEC/CEP levels and downregulation of TEMs, such as Robo4 and endothelial cell-specific chemotaxis regulator (ECSCR), reflecting the formation of torturous tumor vessels." (PMID 26956051, 2016). "Also down regulated in PC3 holoclones was the endothelial cell-specific chemotaxis regulator ECSCR, which when knocked down in tumor xenografts leads to an increase in angiogenesis and could contribute to the increased vascularity seen in the PC3 holoclone-derived tumors." (PMID 21190562, 2010). "Non-tumor components included endothelial cells (expressing VWF, CDH5, ECSCR, SLCO2A1, and MYCT1), pericytes (marked by RGS5, MCAM, and PDGFRB), normal oligodendrocytes (showing PTGDS, MBP, TF, and MOG expression), and TAMs (identified by CD14, AIF1, FCER1G, FCGR3A, TYROBP, and CSF1R)." (PMID 41394801, 2025).
ECSCR also shares sentences with these, for which no sentence is quoted: endothelial dysfunction (1 paper).